INS (insulin)
Diseases named in the same sentence as INS in open-access papers (continued):
Sharing a sentence is not in itself a finding about the gene and the disease.
COVID-19 (continued). "They reported significant alterations in hormone profiles, both at basal levels and after stimulation testing, demonstrating elevated insulin, proinsulin, and C-peptide levels in patients who had recovered from COVID-19 compared to healthy controls." (PMID 38255162, 2023). "Insulin has become the glycemic control agent of choice for hospitalized COVID-19 patients, and its use is mandatory for critically ill patients." (PMID 37168726, 2023). "Acute COVID-19 children had significantly elevated levels of adipsin, leptin, insulin, C-peptide, glucagon and ghrelin in comparison to convalescent COVID-19 and controls." (PMID 37013538, 2023). "Only one male adolescent with poorly controlled T1D, on insulin pump treatment, was hospitalized due to COVID-19 induced severe DKA and discharged 3 days later." (PMID 37435175, 2023). "We measured the pancreatic hormone levels (C-peptide, Insulin and Glucagon) in acute, convalescent COVID-19 and control children." (PMID 37013538, 2023). "In patients with severe COVID-19, the average blood glucose was similar in the 2 study groups (211 ± 88 vs 225 ± 43 mg/dL in insulin-only and other treatment ± insulin groups; P = .3)." (PMID 36701712, 2023). "We found dysregulation in the insulin signaling pathway in hepatocytes, macrophages, and endothelial cells from COVID-19 livers (p<1e-6)." (PMID 37830426, 2023). "Interestingly, insulin usage in patients in intensive care units is associated with increased COVID-19 mortality, possibly linked to increased glycolysis and associated cytokine storm, highlighting the importance and urgency of understanding pathological insulin action in the immune system." (PMID 36992811, 2023). "The hospitals experienced stock out of at least one of the three insulin products for an average of 13(9.5–18) days per month during the outbreak of COVID-19." (PMID 37210502, 2023). "Clinical data have shown that COVID-19 patients require increased insulin doses to maintain glucose control and exhibit significant fluctuations in glucose levels." (PMID 37511334, 2023). "Infection of β-cells in COVID-19 patients results in reduced insulin levels and secretion, as well as cell apoptosis." (PMID 37515156, 2023). "Similar to the liver, we observed insulin pathway enrichment in cardiomyocytes from COVID-19 samples." (PMID 37830426, 2023). "Insulin and IFN-γ, agents associated with COVID-19 severity and outcome, increase SARS-CoV-2 sgRNA expression and translation contingent upon an intact cis-element; disruption of the proposed secondary structure led to loss of agonist-mediated induction." (PMID 38108455, 2023). "The same findings were achieved in terms of blood insulin levels in the case group (both males and females), which demonstrated an increase in insulin production following infection with COVID-19, which was statistically significant (P-value < 0.001)." (PMID 36843827, 2023). "There was moderate to high certainty of evidence that insulin use was associated with an increased risk and use of metformin and GLP-1RA use were associated with a decreased risk of COVID-19-related death." (PMID 37204441, 2023). "Our observations align with these findings: the demand for insulin corresponds to the severity of COVID-19." (PMID 38192935, 2023). "The main difference we observed in the acute phase of COVID-19 was relatively lower insulin secretion 30 and 60 min after glucose loading, suggesting a primary defect in the first phase of the insulin response." (PMID 37460458, 2023). "The findings of our study confirm the higher rate of fatal outcomes in T2DM patients who were treated with insulin before they were infected with COVID-19 [OR = 1.47 (95% CI: 1.43–1.51), p < 0.001]." (PMID 36017317, 2022). "Accordingly, high plasma glucose—a consequence of insulin resistance—is a predictor of a poor COVID-19 prognosis." (PMID 35406000, 2022).
COVID-19 (continued). "Review of the medical records indicated that this girl with COVID-19 was hospitalized with severe ketoacidosis and required intravenous insulin." (PMID 35360001, 2022). "In this study, we evaluated our intravenous insulin infusion protocol for glycemic control in severe COVID-19 patients treated with high-dose methylprednisolone therapy." (PMID 35477646, 2022). "Treatment with metformin or metformin plus sitagliptin ameliorates peripheral IR, insulin sensitivity, and pancreatic β-cell function in COVID-19 patients." (PMID 36355535, 2022). "When diabetic patients are early treated with insulin during COVID-19, they present a better diagnosis disease prognosis, with alleviation of the COVID-19-induced lung injury." (PMID 36439786, 2022). "Although insulin's involvement as an anti-inflammatory factor has been described many years back, its efficacy for COVID-19 patients in terms of cytokine storm relief needs further investigation." (PMID 35530861, 2022). "Kamyshnyi found that patients with diabetes had an aggravated course of disease after COVID-19, while after taking metformin, the insulin sensitivity and blood glucose levels decreased, which further reduced the risk of Corona Virus Disease 2019 (COVID-19)." (PMID 36428983, 2022). "This insulin protocol gradually brought the blood glucose level within target levels in severe COVID-19 patients treated with high-dose steroid." (PMID 35477646, 2022). "The study showed that the IL-6 level was on the rise during the course of COVID-19, whereas that of insulin was on the decrease." (PMID 35530861, 2022). "Of note, glycemic alterations (elevated levels of glucose and insulin) persisted in some of those who had recovered from COVID-19." (PMID 36232381, 2022). "Observational studies clearly show that glycemic control using insulin decreases the rate of important undesired outcomes in patients with COVID-19, such as mechanical ventilation, ICU admission, and death." (PMID 35246230, 2022). "It was demonstrated that COVID-19 mortality is higher in patients taking insulin and lower in patients taking metformin." (PMID 36017317, 2022). "Post-COVID-19 patients (male and female) had higher plasma glucose and insulin levels compared to COVID-19 patients." (PMID 36232381, 2022). "Increased production of chemokines and cytokines by the immune system during COVID-19 also can harm pancreatic β cell function, instilling insulin-glucose-dependent dose sensitivity." (PMID 36439786, 2022). "Due to the inflammatory process in COVID-19, we believed it was essential to evaluate the outcome of inflammation reflected in the changes in interleukin-6 (IL-6) and insulin." (PMID 35530861, 2022). "The available evidence is insufficient to evaluate if the benefits of non-insulin novel antidiabetic drugs in COVID-19 treatment are due to the molecule itself or to the improvement of glycaemic control." (PMID 36289885, 2022). "The moderate and severe COVID-19 patients showed a significant increase (p < 0.001) in glucose, insulin concentrations and HOMA-IR in plasma in comparison with the HS, (respectively)." (PMID 35326383, 2022). "Their findings lend credence to suggestions of compromised insulin secretion and lowered sensitivity to insulin in COVID-19 patients." (PMID 36992767, 2022). "Glucose levels >98.5 mg/dL (AUC 0.852, Sn 83%, Sp 71%, PPV 80%, NPV 76%) and insulin levels >7.4 mUI/mL (AUC 0.950, Sn 94%, Sp 65%, PPV 79%, NPV 89%) were associated with the development of IR in patients with COVID-19." (PMID 36312630, 2022). "Insulin requirement is believed to parallel illness severity in critically unwell COVID-19 patients." (PMID 35530861, 2022). "Most of the severely affected COVID-19 T2DM patients are managed by insulin therapy for more strict blood glucose control." (PMID 36355535, 2022). "The percentage of insulin and trypsin 1 co-stained cells was also greater in samples from COVID-19 patients." (PMID 35053020, 2021).
COVID-19 (continued). "When the liver tissue of patients with COVID-19 is extensively damaged, the ability of liver cells to use glucose to synthesize glycogen is decreased, which leads to the aggravation of insulin resistance and the increase of blood glucose." (PMID 33553435, 2021). "The proinflammatory medium induced by COVID-19 can lead to a high degree of insulin resistance, thus increasing insulin requirements." (PMID 34830623, 2021). "It was reported that insulin decreased disease severity and mortality rates in diabetic COVID-19 patients, possibly due to its anti-inflammatory and immunomodulatory effects and the reduction of blood glucose levels in the patients." (PMID 34157054, 2021). "In the context of COVID-19, increased insulin resistance has been reported even in COVID-19 patients without pre-existing diabetes." (PMID 35053020, 2021). "Large, prospective, randomized, placebo-controlled clinical trials should be performed to elucidate on the harmful effects of insulin therapy in COVID-19 patients." (PMID 34867819, 2021). "The overall data showed that insulin treatment led to increased adverse COVID-19 outcomes, including higher mortality, with moderate heterogeneity (I2 = 69.2%, p<0.001)." (PMID 34367067, 2021). "Pointing to proinflammatory and insulin impairing the action of fetuin-A, its levels were significantly lower in COVID-19 patients despite higher HOMA-IR, CRP, and ferritin levels." (PMID 34680053, 2021). "More importantly, this insulin resistance condition would sustain even after viral elimination, implying a potential long-term pathology in COVID-19 patients." (PMID 34916489, 2021). "In our analysis, a disruption of the regulation of insulin secretion has been observed among the DEGs characterizing COVID-19 and DM." (PMID 34260684, 2021). "Insulin protocols for any COVID-19 patient would therefore have to be explored, developed and clinically tested." (PMID 34395368, 2021). "Nevertheless, hypoglycemic therapy, especially insulin treatment, has remained controversial for patients with COVID-19." (PMID 33859617, 2021). "Our analysis identified the dysregulated process involved in the ‘regulation of secretion’, which indicates that COVID-19 alters the secretory pathways of the pancreas, likely affecting the insulin secretion and impacting the prognosis of DM patients." (PMID 34260684, 2021). "Moderate to high certainty of evidence for higher risk of COVID-19-related death was observed for male sex, older age, CVD, CKD, COPD, high plasma blood glucose at admission and chronic insulin use." (PMID 33907860, 2021). "Although the underlying mechanism is unclear, our meta-analysis results suggest the need for careful assessment of the benefits and potential adverse effects of insulin therapy for patients with COVID-19." (PMID 34603199, 2021). "None of the studies have performed a sensitivity analysis, so there are reasons to believe that prior insulin treatment can identify the severity of the patients' clinical conditions, and hence more prone to COVID-19 mortality." (PMID 34173070, 2021). "For these reasons, a strict insulin therapy is advisable to control the cell and humoral immune impairments in DM patients with COVID-19." (PMID 34124187, 2021). "She achieved well controlled glucose level with oral antidiabetic drugs after receiving intensive insulin therapy and supportive treatment for COVID-19." (PMID 33771154, 2021). "As for the hypoglycaemic therapy given to diabetic patients with COVID-19, all patients received insulin during hospitalization, even those previously treated with oral antidiabetics." (PMID 34201473, 2021). "Here we continue to investigate the effects of inpatient use of T2DM medications, including metformin, acarbose, insulin, and sulfonylureas, on the mortality of COVID-19 patients with T2DM during hospitalization." (PMID 33791691, 2021).
COVID-19 (continued). "Our results suggest that interleukin, TLR, TNF, renin-angiotensin, Fc epsilon RI, insulin signaling, PI3K–Akt signaling pathway, and MAPK signaling are partially shared between COVID-19 and its associated comorbidities." (PMID 34067609, 2021). "Add to this the fact that metformin therapy in DM patients with COVID-19 improves insulin sensitivity, and so it prevents the IR-induced overexpression of pancreatic ACE2." (PMID 34124187, 2021). "Another still uncertain aspect is the use of insulin in hospitalized patients, as worse treatment outcomes have been obtained in patients with COVID-19 treated with insulin compared to patients treated with other antihyperglycemic drugs." (PMID 33801468, 2021). "Here we present two cases of patients with severe Coronavirus Disease (COVID-19) who presented with insulin requirements greater than 5 units/kg." (PMID 33992101, 2021). "It is tempting to propose that Nrf2-interacting foods and nutrients can re-balance insulin resistance and have a significant effect on COVID-19 severity." (PMID 33292691, 2020). "The clinical experience is that diabetic patients affected by COVID-19 quickly struggle to maintain glycaemic control, with significantly increased insulin requirements, and are more prone to diabetic ketoacidosis." (PMID 32379699, 2020). "This study signals towards correlation of intensive glucose monitoring and aggressive insulin regimen to maintain TIR (70–150 mg/dl) with improved ICU outcomes in COVID-19 populations." (PMID 33198177, 2020). "Insulin-based treatment is recommended and cessation of metformin and SGLT2i should be considered for patients with DM and COVID-19 who require hospitalization to avoid the potential adverse effects of these drugs." (PMID 33297431, 2020). "Physicians should be aware that intensive glucose control is required in COVID-19 patients, because of increased insulin requirements as well as higher incidences of hypoglycaemia compared with other critically ill patients." (PMID 32781614, 2020). "A previous study reported that patients with DM who were on insulin therapy required higher doses of insulin and those who were on oral antidiabetics required insulin therapy after admission owing to COVID-19." (PMID 33297431, 2020). "We compared percent time in range of glucose and insulin use as a surrogate for glycemic control amongst COVID-19 and non-COVID-19 ICU patients." (PMID 33198177, 2020). "Finucane and Davenport concluded with suggestions for clinical implications for studying insulin action in relation to COVID-19 severity." (PMID 32733840, 2020). "This suggests that ACE2 appears to be a potentially key molecular link between insulin resistance and COVID-19 severity." (PMID 33308225, 2020). "A higher proportion of COVID-19 patients spent <85% time in range, utilized more insulin per day compared to the non-COVID-19 ICU patients." (PMID 33198177, 2020). "ICU COVID-19 patients spent less time in range (70–150 mg/dL) and required higher daily insulin dose." (PMID 33198177, 2020). "We review the time in range (70–150 mg/dL) spent by critically ill COVID-19 patients and non-COVID-19 patients, along with the daily insulin use." (PMID 33198177, 2020). "Current recommendations for anti-diabetic drugs for diabetic patients with COVID-19 mainly include maintaining previous medication for the mild cases and changing to insulin for regular and severe cases." (PMID 33071977, 2020). "For patients with DM and COVID-19 who require hospitalization, insulin-based treatment is recommended with cessation of metformin and SGLT2i." (PMID 33297431, 2020). "We discuss how these factors collectively contribute to insulin resistance, particularly in the context of COVID-19, and highlight potential therapeutic strategies, such as dietary interventions and ACE2 activators, that may mitigate these effects." (PMID 41890193, 2026).
COVID-19 (continued). "This association might be explained by the cytokine storm induced by severe COVID-19, which can worsen insulin resistance." (PMID 40933377, 2025). "The results demonstrate significant improvements in weight management and cardiometabolic indices in both groups, with the COVID-19 group showing notably better results, including significant reductions in BMI z-score, insulin resistance, blood pressure, and γGT concentrations." (PMID 40647247, 2025). "The increasing absorption band at 1734 cm−1, corresponding to phospholipid and cholesteric esters, strongly supported the suggestion that lipid hydroperoxidation most likely occurred due to oxidative stress caused by COVID-19 in TZD- and insulin-medicated patients." (PMID 40650107, 2025). "Despite the widespread use of corticosteroids in patients with coronavirus disease 2019 (COVID-19) requiring supplemental oxygen, the dose–response relationship between corticosteroid treatment, plasma glucose (PG) levels, and subsequent insulin requirements remains less studied." (PMID 40665171, 2025). "Applying ESPClust to synthetic data, insulin resistance and COVID-19 symptom manifestation, we demonstrate its versatility and ability to uncover nuanced effect size modifications that traditional analyses may overlook." (PMID 39913362, 2025). "In addition, the cytokine storm frequently observed in severe COVID-19 cases also stimulates this kinase family, suppressing insulin signaling and deepening insulin resistance." (PMID 40564201, 2025). "By lowering insulin levels, SGLT2is may help to reduce inflammation and improve outcomes for patients suffering from COVID-19." (PMID 40136608, 2025). "SGLT2is have been shown to have significant beneficial effects on circulating insulinemia and may also influence the course of COVID-19 through their impact on insulin levels and related metabolic processes." (PMID 40136608, 2025). "The role of insulin in patients with COVID-19 and T2DM remains controversial." (PMID 38755442, 2024). "In our study, insulin was higher in the colostrum of mothers suffering from COVID-19." (PMID 38610889, 2024). "The aim of this preliminary study was to explore the mortality-wise effect of insulin and metformin administration in the European (Polish) model of the COVID-19-positive diabetic population sample composed of all patients admitted to the Temporary COVID-19 Hospital in Wroclaw, Poland." (PMID 38540218, 2024). "Disruptions in insulin and glucose metabolism pathways could contribute to neurological symptoms, including brain fog and fatigue reported in long COVID-19, as these pathways are tied to cognitive function." (PMID 39766256, 2024). "Administration of insulin improved outcomes in patients with COVID-19 by achieving glycemic goals, but this hormone might increase mortality and complications in patients with both COVID-19 and DM." (PMID 38378550, 2024). "Our data showed use of insulin (OR 1.411; 95% CI 1.167–1.706) and sulfonylurea (OR 1.226; 95% CI 1.027–1.464) could be related to higher odds of COVID-19 hospitalizations." (PMID 38536830, 2024). "In a recent study of glycaemic control in patients with severe COVID-19 and non-COVID-19 viral pneumonias, we observed that increasing severity of respiratory failure was associated with increased insulin requirements." (PMID 39532941, 2024). "Additionally, patients with COVID-19 had a longer duration of stay with higher insulin requirements on the CII." (PMID 39060948, 2024). "Furthermore, those with COVID-19 were more likely to be younger, have a more normal body weight, consume alcohol (daily, rarely), and use antihypertensive drugs, insulin injections, or hypoglycaemic drugs." (PMID 38397706, 2024). "A role in the onset of systemic, uncontrolled inflammation in COVID-19 can be hypothesized for several mechanisms involved in insulin resistance and inflammation in adipose tissue." (PMID 37934800, 2024).